MIR100HG (mir-100-let-7a-2-mir-125b-1 cluster host gene)
Diseases named in the same sentence as MIR100HG in open-access papers (continued):
Sharing a sentence is not in itself a finding about the gene and the disease.
lung carcinoma (4 papers, 2019 to 2024). "Further Kaplan‐Meier analysis showed that lung cancer patients with low MIR100HG expression had significantly higher survival rates than those with high MIR100HG expression." (PMID 38602284, 2024). "In summary, the novelty of this study is that MIR100HG promotes lung cancer progression by modulating the miR‐5590‐3p/DCBLD2 axis." (PMID 38602284, 2024). "The novelty of this study is that MIR100HG promotes lung cancer progression by modulating the miR‐5590‐3p/DCBLD2 axis." (PMID 38602284, 2024). "Collectively, we highlighted that MIR100HG promoted lung cancer progression by targeting and negatively regulating DCBLD2 through binding with miR‐5590‐3p." (PMID 38602284, 2024). "Colony formation assay also revealed that MIR100HG silencing significantly suppressed the colony formation ability of lung cancer cells." (PMID 38602284, 2024). "The results showed that the expression of MIR100HG was relatively low in non-invasive lung cancer cells, while it was highly expressed in invasive lung cancer cells and other fibroblasts." (PMID 37735657, 2023). "We extracted the relative expression of MIR100HG in lung cancer cells and fibroblasts from the GSE66616 dataset, and compared the expression of MIR100HG in non-invasive and invasive lung cancer cells with other fibroblasts." (PMID 37735657, 2023). "Our study uncovers the complexity of the mechanisms by which lncRNA Mir100hg affects lung cancer metastasis and have enriches our understanding of the molecular and physiological mechanisms by which exosomal non-coding lncRNAs regulate tumor metastasis." (PMID 37735657, 2023). "In our article, we found that MIR100HG was highly expressed in lung cancer tissues and cells, and high expression of MIR100HG was associated with late TNM stage, presence of LNM, and low differentiation in lung cancer patients." (PMID 38602284, 2024). "However, little is known about the role of Mir100hg in lung cancer, and the relationship between Mir100hg and tumor metabolism and tumor-associated exosomes has not been reported." (PMID 37735657, 2023). "We hypothesized that Mir100hg may increase glycolysis through inhibition of miR-15a-5p/miR-31-5p, thereby enhancing the metastatic activity of lung cancer cells." (PMID 37735657, 2023). "Additionally, silencing MIR100HG impeded lung cancer cell proliferation, migration, and invasion." (PMID 38602284, 2024). "Nevertheless, the specific modulatory function of MIR100HG remains unknown in lung cancer." (PMID 38602284, 2024). "Our hypothesis is that cytoplasmic Mir100hg augments the metastatic activity of lung cancer cells by targeting miR-15a-5p and miR-31-5p and acting through the CeRNA regulatory mechanism that leads to the relief of the tumor suppressive activity of miR-15a-5p and miR-31-5p." (PMID 37735657, 2023). "RNA levels of MIR100HG, miR‐5590‐3p, and DCBLD2 in lung cancer tissues and cells were detected by quantitative reverse‐transcription polymerase chain reaction, and protein level was assessed by Western blot." (PMID 38602284, 2024). "MIR100HG and DCBLD2 were highly expressed, while miR‐5590‐3p was lowly expressed in lung cancer tissues and cells." (PMID 38602284, 2024). "Our findings reveal firstly that lncRNA Mir100hg, highly expressed in lung cancer stem cells, can be transferred from cancer stem cells to non-stemness cancer cells through exosomes." (PMID 37735657, 2023). "We first examined the expression of Mir100hg in lung cancer stem cells (LLC-SD) versus non-stemness lung cancer cells (LLC), and we found that Mir100hg was overexpressed in LLC-SD compared to that in LLC cells." (PMID 37735657, 2023).
medulloblastoma (3 papers, 2019 to 2021). A malignant, invasive embryonal neoplasm arising from the cerebellum. "linc-NeD125, also known as MIR100HG, is significantly overexpressed in group 4 MBs, the largest and least well characterized molecular medulloblastoma subgroup." (PMID 31763623, 2019).
prostate carcinoma (3 papers, 2021 to 2025). A carcinoma that arises from epithelial cells of the prostate gland. "In prostate carcinoma PC3U cells, silencing of spliced MIR100HG downregulated expression of mature miR-100 and miR-125b." (PMID 33941855, 2021).
head and neck squamous cell carcinoma (2 papers, 2019 to 2022). A squamous cell carcinoma that arises from any of the following anatomic sites: lip and oral cavity, nasal cavity, paranasal sinuses, pharynx, larynx, and salivary glands. "Recently, MIR100HG was reported to modulate the transforming growth factor beta (TGFβ) signaling pathway, the latter of which is subjugated by HPV in head and neck squamous cell carcinoma and induces epithelial-to-mesenchymal transition in keratinocytes transformed by HPV16." (PMID 36458289, 2022).
idiopathic pulmonary fibrosis (2 papers, 2023 to 2024). Idiopathic pulmonary fibrosis (IPF) is a nonneoplastic pulmonary disease that is characterized by the formation of scar tissue within the lungs in the absence of any known cause. "Similar to our findings, it has been reported that MIR100HG is upregulated in idiopathic pulmonary fibrosis, and MIR100HG knockdown alleviates bleomycin‐induced lung fibrogenesis in mice and TGF‐β1‐triggered fibrotic changes in alveolar epithelial cells." (PMID 38602284, 2024). "MIR100HG has also been found to exert a role in the pathophysiology of dilated cardiomyopathy, intervertebral disk degeneration and pulmonary fibrosis." (PMID 37487022, 2023). "Moreover, animal and in vitro studies have indicated up‐regulation of MIR100HG in bleomycin‐induced pulmonary fibrosis and TGF‐β1‐stimulated type II alveolar epithelial cells of mice, respectively." (PMID 37487022, 2023). "MIR100HG has been upregulated in lung tissues of patients with idiopathic pulmonary fibrosis (IPF)." (PMID 37487022, 2023).
lung adenocarcinoma (2 papers, 2019 to 2021). A carcinoma that arises from the lung and is characterized by the presence of malignant glandular epithelial cells. "Thus, using OncoLnc, Kaplan–Meier analysis revealed that in lung adenocarcinoma and cutaneous melanoma, high expression of both MIR100HG and TGFB1 was linked to long patient survival, suggesting their tumor-suppressive role." (PMID 33941855, 2021). "Using in situ hybridization on a cancer patient tissue microarray, we detected distinct cytoplasmic MIR100HG signals in lung adenocarcinoma, higher expression in malignant melanoma, and even higher in glioma specimen, reflecting the findings of the PanCancer Atlas cohorts." (PMID 33941855, 2021).
acute promyelocytic leukemia (1 paper, 2022). An aggressive form of acute myeloid leukemia (AML), characterized by arrest of leukocyte differentiation at the promyelocyte stage, due to a specific chromosomal translocation t(15;17) in myeloid cells. "Studies on acute promyelocytic leukemia (APL) have reported that the up-regulation of MIR100HG is related to the proliferation of primary APL cells." (PMID 36212400, 2022).
atrial fibrillation (1 paper, 2021). A disorder characterized by an electrocardiographic finding of a supraventricular arrhythmia characterized by the replacement of consistent P waves by rapid oscillations or fibrillatory waves that vary in size, shape and timing and are accompanied by an irregular ventricular response. "Atria-Enriched GJA5, KCNA5 and NPPA, RA-Enriched HCM4, MIR100HG, REC114 and SMAD7 and Ventricles-Enriched KCNJ2, MYH7, PHLDB2, RPL2L and SLC35F1 were associated with atrial fibrillation." (PMID 34088950, 2021).
colon adenocarcinoma (1 paper, 2019). "By analyzing the GEPIA database, we found that the expression levels of MIR100HG, SERTAD4-AS1, and PCAT18 were significantly downregulated; however, KRTAP5-AS1 was upregulated in both colon adenocarcinoma (COAD) and rectum adenocarcinoma (READ) samples compared with that in normal tissues." (PMID 31850052, 2019).
megakaryoblastic leukemia (1 paper, 2014). "Here we show the predominant expression of lincRNAs MIR100HG and MONC in HSPCs and erytroid/megakaryocytic cells and their dysregulation in megakaryoblastic leukemia." (PMID 25027842, 2014).
metastatic disease (1 paper, 2022). "The expression patterns of MIR100HG, hnRNPA2B1 and TCF7L2 in CRC specimens from patients who progressed on cetuximab and patients with metastatic disease were analyzed by RNAscope and immunohistochemical staining." (PMID 35279145, 2022).
myeloid leukemia (1 paper, 2014). A clonal proliferation of myeloid cells and their precursors in the bone marrow, peripheral blood, and spleen. "Our study reveals an unprecedented function of lncRNAs MONC and MIR100HG as regulators of hematopoiesis and oncogenes in the development of myeloid leukemia." (PMID 25027842, 2014).
neuroblastoma (1 paper, 2022). Neuroblastoma (NB) is the most common solid, extracranial childhood tumor. "MIR100HG (alternative name Linc-NeD125) was suggested in human neuroblastoma-derived cells to be specifically induced during neuronal differentiation to support cell survival." (PMID 35462908, 2022).
Obesity (1 paper, 2024). Accumulation of substantial excess body fat. "Similarly, AA regulates the expression of SNHG17 and MIR100HG, known to be deregulated in various human cancers and in obesity, while DHA specifically up-regulates LIPE-AS1, a regulator of adipogenesis in animal models." (PMID 38542331, 2024).
pancreatic adenocarcinoma (1 paper, 2021). "An expression screen for long noncoding RNAs indicated that TGFβ induced mir-100-let-7a-2-mir-125b-1 cluster host gene (MIR100HG) expression in diverse cancer types, thus confirming an earlier demonstration of TGFβ-mediated transcriptional induction of MIR100HG in pancreatic adenocarcinoma." (PMID 33941855, 2021).
prostate adenocarcinoma (1 paper, 2021). "A PanCancer Atlas cohort of 494 prostate adenocarcinoma patients revealed a positive correlation between MIR100HG and TGFB1 expression, and even stronger correlation between MIR100HG and TGFBI expression." (PMID 33941855, 2021).
stomach adenocarcinoma (1 paper, 2021). "Conversely, high MIR100HG and TGFB1 expression correlated with poor survival outcome in stomach adenocarcinoma." (PMID 33941855, 2021).
tumor (26 papers, 2014 to 2025). "More importantly, over‐expression of MIR100HG has been associated with clinical stage, tumour invasion and both lymph and distant metastases in these patients." (PMID 37487022, 2023). "MIR100HG plays a tumor‐driving or tumor‐suppressive role in various cancers, which participates in diverse tumor cell biology processes together with cancer‐related pathways." (PMID 38602284, 2024). "Expressed at high levels in various tumors, MIR100HG enhances oncogenesis as well as tumor progression." (PMID 37735657, 2023). "MIR100HG plays an important role in human tumors and is an lncRNA that has received a lot of attention in the tumors, and it is expressed differently in tumor tissues dependent on the type of tumor." (PMID 35024796, 2022). "MIR100HG played an oncogenic or suppressive role that is involved in various tumor cell biology processes including proliferation, cell cycle, apoptosis, migration and invasion, metastasis, drug resistance, and EMT." (PMID 36212400, 2022). "Meanwhile, dysregulated expression of MIR100HG is markedly correlated with poor prognosis and clinicopathological features including tumor size, AJCC stage, TNM stage, LNM, distant metastasis, prognosis, DFS, OS, and chemoresistance." (PMID 36212400, 2022). "MIR100HG is dysregulated in various cancers and plays an oncogenic or tumor-suppressive role, which participates in many tumor cell biology processes and cancer-related pathways." (PMID 36212400, 2022). "Since TGFβ signaling is known to play both tumor suppressor and protumorigenic roles dependent on the cancer type and stage, we analyzed contributions of MIR100HG and TGFB1 to overall survival of patients with different tumors." (PMID 33941855, 2021). "Increased MIR100HG expression was related to the TNM tumor stage and Edmondson-Steiner grading in HCC patients (P < 0.05)." (PMID 34381502, 2021). "At the same time, the abnormal expression of MIR100HG in these tumors directly regulates the proliferation, migration and invasion of tumor cells." (PMID 35127818, 2021). "The increase in MIR100HG expression was significantly correlated with the tumor histological grade (pathological-T stage, p-value <0.05) and clinical stage (p < 0.05)." (PMID 35127818, 2021). "Taken together, these results suggest that MIR100HG knockdown inhibited tumour growth by increasing miR-5590-3p expression to inhibit the OTX1/ERK/MAPK pathway in vivo." (PMID 33088216, 2020). "To evaluate the function of MIR100HG in tumour growth in vivo, we stably knocked down MIR100HG in MDA-MB-231 cells, which were then subcutaneously injected into nude mice." (PMID 33088216, 2020). "Similarly, evidence has shown that elevated MIR100HG expression is associated with the Edmondson‐Steiner grading and TNM tumor stage in HCC patients." (PMID 38602284, 2024). "Besides, expression of MIR100HG has been positively correlated with grade of tumours and clinical outcome of this type of cancer." (PMID 37487022, 2023). "Interestingly, MIR100HG is a dysregulated emerging ncRNA in multiple tumors, where it can have either an oncogenic or tumor-suppressive role." (PMID 37835380, 2023). "Although MIR100HG participates to regulate the progression of the tumor, the biological function of MIR100HG remains largely unknown." (PMID 36212400, 2022). "This raises the crucial issue of whether MIR100HG is involved in the pathogenesis of other diseases related to aging or high-fat metabolism in addition to tumor diseases." (PMID 36212400, 2022). "As previously stated, MIR100HG may be an oncogenic or tumor suppressor, while the dual role of MIR100HG in cancer may be related to the dual role of TGFβ." (PMID 36212400, 2022). "However, controversial literature also reported that MIR100HG played an important role in reducing the proliferation and invasiveness of tumor cells." (PMID 36212400, 2022). "MIR100HG has been reported to be upregulated or downregulated in different human tumor tissues." (PMID 35127818, 2021).
tumor (continued). "Besides, MIR100HG expression was found to be correlated with the TNM tumor stage and Edmondson-Steiner grading in HCC patients." (PMID 34381502, 2021). "In this study, we not only have identified a set of SA-miRNAs originating from oncogenic MIR17HG and tumor-suppressive MIR100HG clusters as potent controllers of complex and coordinated interactions among several cellular sub-processes associated with cellular senescence." (PMID 28649425, 2017). "Additionally, overexpression of MIR100HG inhibits tumor formation in nude mice in vivo." (PMID 36212400, 2022). "Besides, MIR100HG overexpression remarkably enhances tumor behaviors." (PMID 36212400, 2022). "The expression of MIR100HG, MNX1_AS1, and LINC01016 increased in the later tumor stages (Stage III and Stage IV)." (PMID 38534739, 2024). "The overexpression of lncRNA MIR100HG was related to poor prognosis while downregulation of MIR100HG significantly suppressed TNBC-induced cell proliferation, and reduced tumor growth." (PMID 34830241, 2021). "We found that LBX2-AS1 and MIR100HG were, respectively, upregulated and downregulated in PTC tumor." (PMID 34335744, 2021). "One of 2 TFs, ELK1, is an important regulator and known to activate many lncRNAs including TRPM2‐AS, MIR100HG, and HOXA10‐AS in cancer until now, indicating ELK1 may induce expression of LINC01234 to promote tumor progression in GC too." (PMID 32011780, 2020). "Notably, expression levels of MIR100HG and miR‐204‐5p have been correlated with each other in tumour tissues but not in adjacent non‐cancerous tissues." (PMID 37487022, 2023). "In addition, MIR100HG expression, AJCC stage, T classification, N classification, M classification, and tumor differentiation could be considered independent prognostic factors for DFS and OS." (PMID 36212400, 2022).